MYC (MYC proto-oncogene, bHLH transcription factor)
Diseases named in the same sentence as MYC in open-access papers (continued):
Sharing a sentence is not in itself a finding about the gene and the disease.
cancer (continued). "However, further investigations have shown additive and synergistic activities when used in combination therapies for the treatment of specific cancers in animal models and the potential for synthetic-lethal interactions in MYC-driven cancers specifically has yet to be directly tested." (PMID 23181218, 2012). "This is because cancer cells (including cancer ‘stem’ cells) express strikingly high levels of master lineage-driving transcription factors, yet have paradoxical epigenetic repression of late-maturation MYC-antagonist target genes of these transcription factors." (PMID 23087155, 2012). "In summary, this meta-analysis of nine existing GWAS for solid-cancers indicates a possible cancer risk locus on 8q24 (120,576,000-120,626,000 bp) between NOV and ENPP2, both of which are involved in carcinogenesis and have a regulatory relationship with the proto-oncogene c-MYC." (PMID 22142333, 2011). "When MYC is mutated or over expressed, the protein does not bind correctly and often causes cancer." (PMID 20030818, 2009). "In the current study we sought to determine, whether the expression of TCF7L2 splicing forms we identified in non-cancer colon samples correlated with MYC expression and whether this expression was dependent on alleles of rs6983267 or interaction of rs6983267 with TCF7L2 expression." (PMID 19895682, 2009). "The role of epigenetic modification in cancer induction and differentiation, is gaining several experimental evidences and is giving new perspectives on cellular complex processes: our results can also suggest another mechanism for MYC in promoting oncogenesis through chromatin remodelling." (PMID 18460182, 2008). "Furthermore, the IPA analysis of cancer-specific changes in gene expression networks of MG63 cells revealed significant disruption in the MYC-centered gene expression network, and revealed both genetic and epigenetic abnormalities in a number of genes in this pathway." (PMID 18698372, 2008). "Given the synergistic effects of FGF19 with MYC and KRAS, a therapeutic strategy targeting FGF19, MYC, and KRAS jointly is expected to become a new direction in cancer treatment." (PMID 41328353, 2026). "Among them, we discover the master regulators MYC and MAX that play central roles in cell (de)differentiation and cancer progression to read hmC in a sequence-dependent manner." (PMID 41486423, 2026). "A BRD4 degrader (ZBC260) achieved potent BRD4 depletion at low nanomolar doses, suppressed FOXM1/MYC and HR gene expression, enhanced PARP1 trapping, and produced strong synergy with olaparib, including in patient-derived cancer cells." (PMID 41820523, 2026). "Tumors that overexpress MYC often exhibit heightened sensitivity to CDK4/6 inhibition, making this axis a selective vulnerability in MYC-driven cancers." (PMID 40076599, 2025). "In numerous in vivo and in vitro studies, a variety of cancer-related mRNAs have been identified, including PTEN, ACTB, MAPK4, MKI67, c-MYC, and CD44." (PMID 40082414, 2025). "A deeper understanding of how this regulatory axis is perturbed in different cancers underscores the potential of EGFR, MYC and RAS as promising targets for the development of effective treatments for cancer patients." (PMID 39858030, 2025). "Analysis of data from the Cancer Cell Line Encyclopedia (CCLE) demonstrated a statistically significant inverse correlation between ARID1A and c-MYC expression levels at the transcriptional level." (PMID 41049615, 2025). "Most prior studies on the relationship between MYC and TNBC focused on cancer stem cell properties, finding that MYC activated the Wnt/β-catenin pathway and then initiated cancer stem cell amplification and tumorigenesis." (PMID 40282497, 2025). "MiR-34a targets several oncogenes, including MYC and BCL2, thereby inducing apoptosis and inhibiting cancer cell survival." (PMID 40874062, 2025).
cancer (continued). "The DUB enzymes USP22, USP28 and USP37 interact with MYC in the nucleoplasm and USP36 in the nucleolus and reverse Fbw7a-mediated MYC ubiquitination, which is essential for cancer cell proliferation." (PMID 39858030, 2025). "Based on this analysis, the genes STAT3, MYC, CTNNB1, ESR1, JUN, and BRCA1 emerged as pivotal genes, indicating their significant impact on each cancer type in response to radiation exposure." (PMID 41186627, 2025). "The protein network of unique cancer cell genes in the “cancer cells_vs_all-PDAC” group exhibited top 10 hub genes, including H4C6 (HIST1H4A or HIST1H4C), MYC, H3C12 (HIST1H3A or HIST1H3D), DDX21, USP7, RFC4, APEX1, CDK9, H2BC9 (HIST1H2BH), and NOP2." (PMID 40906153, 2025). "RBPMS inhibits malignant tumor progression by binding to and cleaving ANKRD10 mRNA, which reduces translation to ANKRD10-2 and leads to a decrease in MYC transcriptional activity." (PMID 40044952, 2025). "YTHDF1, a key m6A reader, acts as an oncogenic driver in multiple cancers by modulating mRNA translation and stability, but its role in NPC, especially its mechanism of regulating critical oncogenes like c-MYC, remains poorly defined." (PMID 41167308, 2025). "PD-L1 expression in cancer cells is regulated by a variety of transcriptional factors including hypoxia-inducible factor–1α, nuclear factor κB, STAT1, and MYC." (PMID 40779629, 2025). "DANCR levels correlate with essential growth regulatory genes including c-MYC across CCLE cancer cell lines and it is highly expressed in many different types of cancer." (PMID 41336739, 2025). "Many studies have shown that STAT3 induces the transcription of genes involved in cancer cell proliferation and survival, such as CCND1, BCL2, and MYC." (PMID 41104968, 2025). "For example, studies have shown that MYC can upregulate integrin β1 (ITGB1), which enhances the attachment of cancer cells to the ECM and facilitates their invasive potential." (PMID 40076599, 2025). "RAF proteins play a pivotal role in cancer progression, as oncoproteins such as RAS, MYC, and RAF can paradoxically induce apoptosis or senescence when signaling is excessively activated." (PMID 40141317, 2025). "Additionally, we explore how different types of ncRNAs may collaborate or influence each other’s roles in MYC regulation and metabolic function, aiming to identify biomarkers and synthetic lethality targets to disrupt MYC-driven metabolic reprogramming in cancer." (PMID 40126351, 2025). "In conclusion, our data collectively implicate PVT1 as a crucial hub regulating MYC potency by modulating both AKT and MAPK activity in human cancer." (PMID 40027648, 2025). "In tumors driven by MYC overexpression, CDK2 activity is vital for preventing senescence and enabling cancer cell immortalization." (PMID 39800748, 2025). "We confirmed that the expression levels of AXL and CYR61, target proteins of YAP/TAZ signaling, as well as the expression levels of c-MYC and KLF4, factors representing the cancer cell undifferentiated state, were similarly decreased." (PMID 39604563, 2025). "The three cell lines used in the present study were derived from different mouse cancers: PY8119 from TNBC, M158 from c-MYC-overexpressed, and NF639 from c-neu-overexpressed mammary gland tumor." (PMID 41051525, 2025). "The methyltransferase NSUN7 is primarily recognized for its role in cancer, where it methylates the mRNA of CCDC9B (Coiled-Coil Domain Containing 9B) and reduces MYC expression." (PMID 41516134, 2025).
cancer (continued). "To explore these concepts further and the potential of SAE inhibitors to target MYC-addicted cancers, we set out to better understand the relationship between SUMO signaling and MYC overexpression." (PMID 40487451, 2025). "Mechanistically, this synthetic lethality is driven by the fact that MYC promotes both mitochondrial OXPHOS and glycolysis, thus providing cancer cells with high metabolic flexibility." (PMID 40668928, 2025). "Since STAT3, MYC, and EBNA1 are each essential for survival and proliferation of EBV-transformed and cancer cells, we tested the effects of the three inhibitors on cell viability and apoptosis in EBV+ HH514–16 BL cells." (PMID 40354417, 2025). "By identifying the synthetic lethal partner of GSPT1, researchers hope to identify more sensitive indications for targeting GSPT1, including MYC, IKZF1/3, BTK, AR/ARv7, and mTOR‐driven cancers." (PMID 41194439, 2025). "The molecular control of cancer cell aerobic glycolysis is predominantly governed by a network of oncogenic signaling pathways, with PI3K/AKT and MYC serving as core regulatory factors." (PMID 40754534, 2025). "In cancer, GSK3β is a crucial component of several oncogenic signaling pathways, such as the WNT/β-catenin, Hedgehog (HH), Notch and MYC pathways." (PMID 39762409, 2025). "Collectively, oncogenic MYC, PI3K/Akt-mTORC1, and Ras–ERK/MNK signalling drive ribosome production and translational output to promote cancer cell proliferation, survival, and metastasis." (PMID 40805230, 2025). "In the context of cancer, EBNA1 also influences gene expression, promoting the upregulation of genes such as c-MYC and E2F1 through PI3Kδ and BRD7." (PMID 40354417, 2025). "Consistent with earlier research, the proto-oncogene MYC was recognized as a target of GAPDH, directly influencing the growth and proliferation of cancer cells." (PMID 41175344, 2025). "Dysfunctional MYC genes, including C-MYC and N-MYC, which are pivotal regulators of cellular proliferation, have been identified in approximately 70% of human cancers." (PMID 40746825, 2025). "TFs like MYC and SOX2, vital for cellular reprogramming, also drive oncogenic transformation, underscoring their role in cancer’s aggressive traits." (PMID 40016470, 2025). "CUDC-907, a novel dual inhibitor targeting the MYC upstream pathway (HDAC/PI3K), shows significant antitumor efficacy across multiple cancer types." (PMID 40229260, 2025). "Compound sensitivity across cancer cell lines correlates with dependency on the RBP RBM42, which has been shown to bind to the MYC 5′ UTR and enhance its translation." (PMID 40943063, 2025). "Although this study supports the role of EGR3 as an oncogenic driver in GBM by promoting cell growth and upregulating MYC and CDK1, its function in cancer appears to be complex and context-dependent." (PMID 40649712, 2025). "Overall, p62 showed broad positive correlations with several oncogenic and metabolic pathways in most cancers, including oxidative phosphorylation, ROS pathway, UPR, MYC targets v2, DNA repair, and mTORC1 signaling." (PMID 41291343, 2025). "The cancer cell stemness reprogramming factors OCT4, KLF4 and c‐MYC and the stem cell marker CD44 were significantly increased in Huh7 cells on the 14th day after HBx overexpression." (PMID 40717222, 2025).
cancer (continued). "For instance, MYC directly regulates expression of key HR components such as RAD51, BRCA1, and BRCA2 in multiple cancer contexts." (PMID 41561634, 2025). "Our findings reveal a novel regulatory axis in EBV-positive cancer cells involving STAT3, MYC, EBNA1, & ZC3H18, also linking ZC3H18 to the NF-κB pathway independently of LMP1." (PMID 40354417, 2025). "Previous studies have shown that lactate uptake and mitochondrial metabolism are upregulated by c‐MYC, MCT1, and TIGAR, and lactate export is mediated by MCT4 and is highly expressed in glycolytic cancer cells." (PMID 39996379, 2025). "In fact, greater than 7% (730/9,950) of human cancers had co-amplification of both HSF1 and MYC genes, which was a statistically significant co-occurrence using a Fisher exact test (P < 0.0001)." (PMID 39831777, 2025). "The c-MYC oncogenes family (MYC, MYCN, MYCL) plays a pivotal role in tumorigenesis, particularly in cancers characterized by MYC overexpression or amplification." (PMID 40710353, 2025). "This is consistent with reports demonstrating MYC’s involvement in UPR regulation and its contribution to cancer development and progression." (PMID 40718795, 2025). "Exosomal miR-105 from MYC-expressing cancer cells reprograms CAF metabolism, fueling nearby cancer cell growth." (PMID 40230452, 2025). "This stabilization can physically impede the cellular machinery required for c-MYC gene expression, effectively reducing c-MYC levels and hindering cancer cell proliferation." (PMID 40430538, 2025). "In summary, we identify PVT1 as a complex molecular hub that orchestrates the interplay between MYC, mTOR, AKT, and RAS signaling in cancer." (PMID 40027648, 2025). "The expression profiles of mTOR, MYC and RAS, which are important signaling pathways in cancer progression, were examined at the mRNA level." (PMID 40566531, 2025). "Notably, the MYC, E2F2 and CASP8 genes, which are important regulators of the cell cycle and apoptosis and have previously been implicated in HPV-related processes or cancer 31-33, were identified as common trans-interaction sites in both the HiC and 4C datasets." (PMID 40568071, 2025). "Regarding genetic instability, the genes SOX2, OCT3/4, c-MYC, and KLF4—commonly used for reprogramming somatic cells to iPSCs—are often expressed at higher levels in various cancer cells and are involved in the development and progression of several cancers." (PMID 40541178, 2025). "Our study provides novel insights into the role of PA2G4 as a critical regulator of c-MYC stability and underscores its potential as a therapeutic target across MYC-driven cancers." (PMID 41002386, 2025). "Our results identify MYC/PVT1 amplification and PVT1 translocation as key drivers of cancer pathogenesis, reshaping the oncogenic signaling landscape through the expression—or lack thereof—of previously uncharacterized short proteins." (PMID 40027648, 2025). "In summary, PPARδ integrates microenvironmental signals to reprogram PDAC cell metabolism via the MYC/PGC1A axis, thereby promoting cancer cell invasiveness and in vivo metastasis in PDAC." (PMID 40607925, 2025). "Immunoprecipitation analysis revealed that ATF5 binds to MYC in KP4 cells on both stiff and soft ECMs, suggesting that in cancer cells on stiff ECMs, highly expressed MYC binds to ATF5 and localizes to the nuclei with ATF5." (PMID 40124511, 2025). "The hypoxia-associated signaling pathways can trigger the HIF-dependent expression of molecules like KLF4, MYC, OCT4, SOX2, and NANOG, which can enhance cancer stemness and inhibit cancer cell differentiation." (PMID 39928285, 2025).
cancer (continued). "BMS-986158, a highly selective and potent inhibitor of BRD2/BRD4, has demonstrated anti-cancer activity through the downregulation of BRD4 and c-MYC expressions in preclinical efficacy studies and a clinical trial for patients with solid tumors (NCT02419417)." (PMID 40937321, 2025). "Therefore, targeting cholesterol synthesis might be an option for MYC-driven cancers." (PMID 38853928, 2025). "Given that proto-oncogenes such as MYC, KRAS, RET, and VEGF are often overexpressed in human cancers, we analyzed the regulatory effect of BTO-28 on proto-oncogene transcription in HT-29 cells." (PMID 40966493, 2025). "and The Cancer Genome Atlas (TCGA)‐LUAD mRNA data, revealed a significant activation of the MYC pathway in the MP‐subtype LUAD compared to that in the AC subtype." (PMID 39899538, 2025). "Glycolysis in cancer cells is modulated by important transcription factors and pathways, such as the HIF‐1α, AMP‐activated protein kinase (AMPK) and c‐MYC pathway." (PMID 39993964, 2025). "The identification of MYC-driven metabolic reprogramming, mediated by fibroblast-derived signals, highlights the crucial role of the TME in shaping cancer cell behavior." (PMID 41234356, 2025). "The frequency of amplification of MYC, MYCL, or MYCN is 28% across 33 different forms of human cancer in The Cancer Genome Atlas (TCGA) project." (PMID 40290126, 2025). "The RCC score includes a panel of 12 genes, with 7 cancer-related genes (stromal genes: INHBA, BGN, and cell cycle genes: MKI67, MYC, MYBL2, GADD45B) and 5 reference genes, and is used to predict CRC recurrence." (PMID 40664638, 2025). "Further, SOX2, KLF4 and c-MYC are particularly important in regulating migration and invasion, often through pathways related to EMT, with implications in both development and cancer metastasis." (PMID 40019880, 2025). "The formation of G4s in these key regulatory regions, such as those found in c-MYC, KRAS, and others, has been associated with reduced gene expression, further suggesting that targeting these G4 structures could serve as an effective approach for anti-cancer therapies." (PMID 40333779, 2025). "Our results identify that these cancer metabolism-related gene sets and signaling pathways are closely related to SLC35A2-regulated MYC, indicating that SLC35A2-MYC holds an important role in CRC progression." (PMID 40303483, 2025). "Future research will focus on exploring how ART exerted its anti-cancer effects in BLCA through targeting the MYC, which will help better understand ART’s anti-cancer mechanism and provide a theoretical basis for developing new cancer treatment strategies." (PMID 40303931, 2025). "In summary, UBR5 interacts with key proteins such as MOAP-1, MOIP-1, β-catenin, TXNIP, MYC, CDC73, CAPZA1, TIP60, GKN1, and ECRG4, NF-kB, highlighting its pivotal roles in promoting metastasis, therapeutic resistance, and cancer cell survival." (PMID 39857943, 2025). "Among them, Zn-DIGP bearing a zinc (II) cation in its structure was studied and properities of the theranostic fluorescent probe were observed with a down-regulation of c-MYC and KRAS expression in cancer lines (compound 37)." (PMID 41157115, 2025). "In this article, we show that Omomyc, the only direct MYC inhibitor to reach a phase 2 clinical trial so far, can induce DDR defects and DNA damage in cancer cells and propose it as a cutting-edge therapeutic opportunity to overcome PARPi resistance." (PMID 41273720, 2025). "Although FOXA1 and MYC had a less significant correlation with integrin genes, ERG showed an overwhelmingly positive correlation with them in pan-cancer, pointing ERG as an essential upstream TF of integrins." (PMID 39436262, 2024).